ZNF616 (zinc finger protein 616)
Description:
May be involved in transcriptional regulation.
Synonyms: MGC45556
Tractability: PROTAC: ubiquitination databases record sites on it.
Gene: Protein-coding gene on chromosome 19 (52,113,073 to 52,139,965, reverse strand). Ensembl gene ENSG00000204611.
Subcellular location: Nucleus
Subcellular location (Human Protein Atlas): Centrosome
Pathways (Reactome):
Gene expression (Transcription): Generic Transcription Pathway
Gene Ontology:
Molecular function: DNA-binding transcription factor activity, RNA polymerase II-specific; RNA polymerase II cis-regulatory region sequence-specific DNA binding; sequence-specific double-stranded DNA binding
Biological process: regulation of transcription by RNA polymerase II; regulation of DNA-templated transcription; regulation of gene expression
Cellular component: nucleus; cytoplasm
Genetic constraint (gnomAD): Loss-of-function variants: 5 observed, 8.1 expected, observed/expected ratio (o/e) 0.62, 90% interval 0.32 to 1.29. That is too few expected variants to judge how well the gene tolerates losing a copy. Missense variants: 913 observed, 993.93 expected, observed/expected ratio (o/e) 0.92, 90% interval 0.87 to 0.97. Synonymous variants: 319 observed, 333.29 expected, observed/expected ratio (o/e) 0.96, 90% interval 0.87 to 1.05.
Homologues: Orthologues: chimpanzee ZNF616 (98% identical), macaque ZNF616 (97% identical). Paralogues in human: ZNF841 (44% identical), ZNF836 (44% identical), ZNF546 (39% identical), ZNF267 (37% identical), ZNF528 (37% identical), ZNF28 (36% identical), ZNF30 (36% identical), ZNF33A (36% identical), ZNF658 (35% identical), ZNF470 (35% identical), ZNF254 (35% identical), ZNF534 (35% identical), and 164 more.
Diseases named in the same sentence as ZNF616 in open-access papers:
ZNF616 is named in the same sentence as 1 disease in open-access papers, as found by Europe PMC text mining. Sharing a sentence is not in itself a finding about the gene and the disease. The quoted sentences say what the papers report.
breast carcinoma (1 paper, 2017). "Similarly, miR-7641 inhibition in MDA-MB-231 breast cancer cells upregulated RPS16, TNFSF10, MSRB3, CDNF, ZNF616, and NBEA, downregulated CUL3, and showed no remarkable changes for PIGC and the other genes." (PMID 28827731, 2017).